GNB1L (G protein subunit beta 1 like)
Description:
Acts as a critical regulator of DNA damage response (DDR) signaling via specifically regulating phosphatidylinositol 3-kinase-related protein kinase (PIKK) family proteins.
Synonyms: WDVCF; GY2; WDR14; FKSG1; DGCRK3
Tractability: PROTAC: ubiquitination databases record sites on it; its protein half-life has been measured.
Target class: Reader; Epigenetic regulator; Methyl-lysine/arginine binding protein; WDR domain
Gene: Protein-coding gene on chromosome 22 (19,783,223 to 19,854,939, reverse strand). Ensembl gene ENSG00000185838.
Subcellular location: Cytoplasm; Nucleus
Subcellular location (Human Protein Atlas): Cytosol
Gene Ontology:
Biological process: DNA damage checkpoint signaling; DNA damage response
Cellular component: cytoplasm; nucleus
Genetic constraint (gnomAD): Loss-of-function variants: 24 observed, 33.1 expected, observed/expected ratio (o/e) 0.73, 90% interval 0.52 to 1.02. The upper end of that interval is the gene's LOEUF score, 1.02, which puts it in group 4 of 6, group 1 being the genes least tolerant of losing a copy. Missense variants: 419 observed, 474.62 expected, observed/expected ratio (o/e) 0.88, 90% interval 0.81 to 0.96. Synonymous variants: 193 observed, 212.13 expected, observed/expected ratio (o/e) 0.91, 90% interval 0.81 to 1.02.
Homologues: Orthologues: chimpanzee GNB1L (98% identical), dog GNB1L (83% identical), pig GNB1L (83% identical), guinea pig GNB1L (82% identical), rabbit GNB1L (81% identical), mouse Gnb1l (80% identical), rat Gnb1l (79% identical), tropical clawed frog gnb1l (54% identical), zebrafish gnb1l (51% identical). Paralogues in human: TBL3 (23% identical).
Diseases named in the same sentence as GNB1L in open-access papers:
GNB1L is named in the same sentence as 15 diseases in open-access papers, as found by Europe PMC text mining. Sharing a sentence is not in itself a finding about the gene and the disease. The quoted sentences say what the papers report.
schizophrenia (7 papers, 2008 to 2022). A major psychotic disorder characterized by abnormalities in the perception or expression of reality. "PRODH catalyzes a step in the conversion of proline to glutamate, while GNB1L encodes a G-protein beta-subunit-like polypeptide; both genes have also been associated with schizophrenia and other mental disorders." (PMID 32339168, 2020). "All of these factors motivated our evaluation of the contribution of GNB1L variants to autism and schizophrenia." (PMID 22095694, 2012). "We identified decreased expression of several genes (among which COMT, Ufd1L, PCQAP, and GNB1L) previously linked to schizophrenia as well as involvement of signaling pathways relevant to schizophrenia, of which Neurotrophin/Trk and neuregulin signaling seems to be especially notable." (PMID 22457764, 2012). "Haplotypes comprised of high- or low-expression alleles of regulatory variants or iSNPs would provide the best genetic markers to test the hypothesis that differential expression of GNB1L contributes to risk of developing schizophrenia." (PMID 22013986, 2011). "Most studies on GNB1L are related to psychiatric disorders reported, for example, in schizophrenia and autism." (PMID 36428851, 2022). "Copy number evaluations and direct DNA sequencing of GNB1L in 271 schizophrenia and 513 autism cases revealed dup22q11.2 in two families with autism and private GNB1L missense variants in conserved residues in three families (P = 0.036)." (PMID 22095694, 2012). "We sequenced the 6 coding exons and splice junctions of GNB1L in genomic DNA of 271 subjects with schizophrenia and 513 subjects with ASD." (PMID 22095694, 2012). "Several genes located in the 22q11 region have been linked to schizophrenia, including COMT, ProDH, Ufd1L, PCQAP, and, recently, GNB1L." (PMID 22457764, 2012). "Among these are the genes which have been previously associated with schizophrenia, COMT, Ufd1L, PCQAP, and GNB1L." (PMID 22457764, 2012). "Our second assumption was that rare coding sequence changes in GNB1L might be responsible for the phenotype in a subset of ASD or schizophrenia cases." (PMID 22095694, 2012). "Prior studies provided evidence that GNB1L may have a role in schizophrenia." (PMID 22095694, 2012). "The disruption of GNB1L by a balanced translocation in the del22q11.2 region in our proband with ASD as a child and schizophrenia as a young adult suggests that this gene might play a role in neurobehavioral phenotypes." (PMID 22095694, 2012).
autism (4 papers, 2012 to 2022). Persistent deficits in social interaction and communication and interaction as well as a markedly restricted repertoire of activity and interest as well as repetitive patterns of behavior. "The unique GNB1L variants in our families with autism were all inherited." (PMID 22095694, 2012). "Our findings are consistent with the hypothesis that GNB1L mutations are risk factors in a multigenic threshold model for autism." (PMID 22095694, 2012). "The importance of this region in autism has been recently highlighted by the identification of two autism candidate genes, TBX1 and GNB1L." (PMID 23840741, 2013).
DiGeorge syndrome (3 papers, 2012 to 2023). "22q11 proximal deletion, also known as DiGeorge syndrome or velocardiofacial syndrome, involves more than 30 Mendelian genes; potential genes such as TBX1, COMT, UFD1L, GNB1L, TRXR2, MED15, and RANBP1 were researched to explore the phenotype/CNV correlation." (PMID 32863884, 2020).
autism spectrum disorder (2 papers, 2012 to 2023). A spectrum of developmental disorders that includes autism, and Asperger syndrome. "For autism spectrum disorder, DGCR2, ARVCF, GNB1L, COMT, ZDHHC8, CHRNA7, and NRXN1 are candidate genes with various associated developmental defects." (PMID 37486921, 2023).
breast carcinoma (1 paper, 2024). "Both TMEM132B and GNB1L have been reported to take part in breast cancer development and progression." (PMID 39409914, 2024). "In-depth research is required to explore the roles of TMEM132B and GNB1L in breast cancer progression, especially their involvement in pathways related to tumor invasion and metastasis." (PMID 39409914, 2024). "Our analysis suggests that dysregulated activation of TMEM132B or GNB1L may contribute to worse progression, which was particularly prominent in Black breast cancer participants." (PMID 39409914, 2024).
glaucoma (1 paper, 2024). Increased pressure in the eyeball due to obstruction of the outflow of aqueous humor. "Regarding the genetic aspect, SNPs with high OR values for glaucoma exposure on cataract were TMCO1-AS1 (rs2814471 with OR = 1.370), GAS7 (rs12602519 with OR = 1.178), ABCA1;SLC44A1 (rs2472493 with OR = 1.162), and GNB1L;TXNRD2 (rs58714937 with OR = 1.153)." (PMID 38674349, 2024).
RASopathy (1 paper, 2017). Developmental syndromes caused by germline mutations (or in rare cases by somatic mosaicism) in genes that alter the Ras subfamily and mitogen-activated protein kinases that control signal transduction. "Additional genes listed in SFARIgene adjacent to our top RASopathy social responsiveness QTL results include CNTN5, ESRRB, GABRB1, GNB1L, and ICA1." (PMID 28076348, 2017).
cancer (3 papers, 2022 to 2024). A tumor composed of atypical neoplastic, often pleomorphic cells that invade other tissues. "Similarly, GNB1L, a member of the G protein family, may impact signaling pathways related to cancer cell growth, survival, and metastasis." (PMID 39409914, 2024). "In our study, we found overexpression of GNB1L (G protein beta 1 subunit) in the cell lines and ALL patients; however, there are no reports in the literature that have studied the expression of this gene in any type of cancer." (PMID 36428851, 2022).
tumor (2 papers, 2024). "Some other CpGs/genes differentiating these tumor groups were also engaged in neuronal processes (ZIC2, GNB1L)." (PMID 39456618, 2024).
neurodevelopmental disorder (1 paper, 2012). A behavioral and cognitive disorder with onset during the developmental period that involves impaired or aberrant development of intellectual, motor, or social functions. "As GNB1L lies in the critical del22q11.2 region it is a priori a candidate gene for neurodevelopmental disorders that occur in the associated CNV syndromes." (PMID 22095694, 2012).
GNB1L also shares sentences with these, for which no sentence is quoted: mental disorder (2 papers); cleft lip (1); cleft palate (1); diseases of the larynx and vocal cords (1); leukemia (1).